MERTK (MER proto-oncogene, tyrosine kinase)
Diseases named in the same sentence as MERTK in open-access papers (continued):
Sharing a sentence is not in itself a finding about the gene and the disease.
melanoma (continued). "However, when incubated with PLX, the colony formation was severely impaired in three different MERTK-depleted melanoma cell lines A375p, A2058 and SKMel100, all of which were associated with an increased pro-apoptotic potential." (PMID 29050198, 2017). "MerTK was recently proposed as a potential therapeutic target in melanoma." (PMID 29050198, 2017). "To examine whether autophagy-mediated MerTK activation could be mediated by mTORC1, we exposed melanoma cells to the pharmacological allosteric inhibitor rapamycin." (PMID 29050198, 2017). "To investigate whether vemurafenib-elicited MerTK upregulation leads to restoration of proliferation in resistant cell populations, we generated resistant melanoma cell lines A375R and A2058R that were exposed to BRAFi for 2 months." (PMID 29050198, 2017). "Thus, in the context of mutant BRAF inhibition in melanoma, the activation of Zeb2/MerTK signaling plays an important role in mediating cancer cell survival and resistance." (PMID 29050198, 2017). "Moreover, UNC1062 induced apoptosis and reduced MERTK-mediated downstream signaling as well as invasion in melanoma cells and proliferation in gastric cancer cell lines." (PMID 27081701, 2016). "However, in melanoma and non-small cell lung cancer xenograft mouse models knockdown of MERTK led to impaired proliferation." (PMID 27081701, 2016). "The association of MERTK with cell motility has previously been shown in melanoma, glioblastoma and non-tumorigenic breast epithelial cell lines." (PMID 27081701, 2016). "Moreover, MERTK has been described as a potential therapeutic target in melanoma, astrocytoma as well as gastric and prostate cancer." (PMID 27081701, 2016). "Therefore, the overexpression of MERTK has been detected in numerous cancers, including myeloid and lymphoblastic leukemias, breast cancer, non-small cell lung cancer, brain cancers, melanoma, prostate cancer, liver cancer, colorectal cancer, gastric cancer, ovarian cancer, and rhabdomyosarcomas." (PMID 33562150, 2021). "In the here used human M-MDSC model, we observed that upon exposure to melanoma CM, moMDSCs further acquired a suppressive phenotype, characterized by the upregulation of CD14, CCR5, MerTK, and the downregulation of HLA-DR and CD86." (PMID 38343540, 2024). "It has been reported that MerTK promotes cell invasion in glioblastoma multiforme (GBM) and melanoma." (PMID 38791148, 2024). "This suggests that Tyro3, Ax1 and MERTK control the function of MDSC and are expected to be pharmacological targets for regulating MDSC-mediated immunosuppression in patients with melanoma." (PMID 37221594, 2023). "Tyro3, Axl, and MerTK control myeloid-derived suppressor cell (MDSC) functionality, regulate MDSC-mediated immune suppression and augment anti-PD-1 therapy in melanoma patients, which highlights the role of these molecules in antitumor therapy." (PMID 36059952, 2022). "For example, inhibiting a novel NRAS-activating kinase (STK19) and combining MEK inhibitors with inhibitors of the MER receptor tyrosine kinase (MERTK), BET, and HDAC have been reported to block NRAS mutant melanoma growth in vitro and in vivo." (PMID 33921974, 2021). "MerTK/FLT3-specific small molecule inhibitors UNC2025, MRX2843 and UNC1666 were shown to have significant effect on tumor growth of AML, ALL and melanoma in cell lines, murine models and primary patient tumor samples." (PMID 33801886, 2021). "Here we show that BRAFi induces upregulation of MerTK, a master regulator of phagocytosis, which contributes to acquired resistance to BRAF inhibition in BRAFV600E melanoma." (PMID 29050198, 2017). "In a study dealing with the MerTK (+) melanoma cells, UNC1062 induced cell death similar to the current study, and it also inhibited migration and invasion of the melanoma cells." (PMID 29228560, 2017). "Inhibition of MERTK with a synthetic compound UNC1062 inhibits invasion and induces apoptosis in melanoma cells in vitro." (PMID 24743024, 2014).
melanoma (continued). "MerTK is highly expressed in several types of cancer, such as non–small-cell lung cancer (NSCLC), breast cancer, colorectal cancer, glioblastoma multiforme (GBM), melanoma, acute myeloid leukemia (AML), and schwannoma." (PMID 41226428, 2025). "To understand the signals that impel primary melanoma tumors to become metastatic, we determined the expression of TAM family members (Axl, Tyro3 and MerTK) in melanoma cell lines including vertical growth phase (VGP) and metastatic growth phase (MGP) using immunoblotting." (PMID 36989239, 2023). "In the present study, we found that melanoma cell lines present variable protein levels of Axl and Tyro3; interestingly, MerTK is not noted at detectable levels in any of tested MGP (metastatic growth phase) cell lines." (PMID 36989239, 2023). "In addition, MERTK contributes to the oncogenesis of a spectrum of human cancers, including hematological malignancies, glioblastoma, NSCLC, melanoma, breast cancer, colon cancer, gastric cancer, and prostate cancer." (PMID 33562150, 2021). "MerTK overexpression was demonstrated not only in melanomas resistant to BRAFi monotherapy (5 out of 10 samples from melanoma patients) but also in melanoma resistant to BRAFi+MEKi (1 out of 3), although MEKi alone does not affect MerTK." (PMID 29050198, 2017). "SAM also identified MERTK—a receptor tyrosine kinase correlating with disease progression in melanoma and not detected in the full proteome measurements—to be differentially expressed between the different Kinobeads Subtypes (q‐value < 0.01)." (PMID 29101300, 2017). "Therapy-induced overexpression of MerTK on the plasma membrane was dependent of the time-course and occurred after 48 hours of BRAFi-treatment in 50% (8 out of 16) of the examined BRAF mutant human melanoma cell lines." (PMID 29050198, 2017). "Due to tumour relapse in vivo, mice injected with MerTK-depleted A375p melanoma cells did not have longer survival, and isolated CQ-treatment did not induce tumour regression." (PMID 29050198, 2017). "Basal MerTK was exclusively detected in melanomas but not in benign melanocytic nevi." (PMID 29050198, 2017). "Moreover, although melanoma cell lines resistant to single-agent MEKi did not upregulate MerTK, ∼30% (1 out of 3) paired human melanomas with acquired resistance to combined BRAFi+MEKi therapy showed elevated MerTK expression." (PMID 29050198, 2017). "MerTK, a lesser studied TAM member, is not readily detectable in melanoma cell lines except in two VGP cell line 983A and FEMX." (PMID 36989239, 2023). "Ectopic expression of TYRO3 in the MCF10A breast cancer cell line induced AKT phosphorylation in the presence of GAS6 and treatment with GAS6 promoted AKT phosphorylation in the MDA-MB435 melanoma cell line, which expresses TYRO3 but not MERTK or AXL." (PMID 30501104, 2018).
atherosclerosis (38 papers, 2015 to 2025). A disease characterized by the build-up of fatty material and calcium deposition in the arterial wall resulting in partial or complete occlusion of the arterial lumen. "Collectively, these data indicate that the aPC-mediated amelioration of diabetes-associated atherosclerosis depends on MerTK-mediated macrophage efferocytosis." (PMID 41083981, 2025). "Our recent studies showed that primary aortic ECs have a high ability to perform efferocytosis via MerTK and play an important role in vascular aging and atherosclerosis, the diseases that are closely associated with AAAD 14-16." (PMID 39744231, 2025). "Our findings revealed that endothelial MerTK deficiency significantly accelerates the development of atherosclerosis." (PMID 40953531, 2025). "Mutations in tyrosine kinase-defective Mertk receptor MERTK decreases macrophage autophagy and increases the size of necrotic plaque in atherosclerosis." (PMID 38984353, 2024). "Our proteomics and immunostaining show that d-flow impairs engulfment and phagocytosis of red blood cells, and MerTK gene deficiency aggravates endothelial dysfunction in atherosclerosis." (PMID 38646649, 2024). "Conversely, MerTK is cleaved in advanced atherosclerosis and MerTK deficiency is associated with increased infarct size and cardiac dysfunction." (PMID 38341954, 2024). "MERTK is known to contribute to the oncogenesis of various human cancers and has been linked to atherosclerosis and diabetes." (PMID 39334377, 2024). "Single nucleotide polymorphisms (SNPs) in MERTK also leads to a range of chronic inflammatory and autoimmune diseases, most notably, atherosclerosis and MS." (PMID 33912166, 2021). "Other mutations in MERTK and its opsonin, Gas6, are associated with increased susceptibility towards atherosclerosis and autoimmune disorders including multiple sclerosis and SLE." (PMID 34065321, 2021). "Similar to multiple sclerosis, polymorphisms in MERTK and Gas6 are also associated with atherosclerosis." (PMID 34065321, 2021). "One mechanism is linked to impaired efferocytosis in advanced atherosclerosis via the proteolytic cleavage of the key receptors, MERTK and LRP1, which increase plaque necrosis." (PMID 32346605, 2020). "Whereas MerTK deficiency promotes defective efferocytosis, inflammation, and plaque necrosis in advanced murine atherosclerosis, the role of Axl in advanced atherosclerosis progression is not known." (PMID 27958361, 2016). "However, recent studies have shown that aortic ECs have a high ability to perform efferocytosis via MerTK in atherosclerosis and vascular aging, two diseases closely associated with AAAD 12-16." (PMID 39744231, 2025). "Interestingly, our recent reports demonstrated that primary aortic ECs have a high ability to perform efferocytosis via MerTK and play an important role in aortic aneurysms and dissections, the diseases that are closely associated with atherosclerosis." (PMID 40953531, 2025). "Importantly, recent studies from us and other research groups have confirmed that aortic ECs can highly express MerTK and play a key role in aortic aneurysms and dissections, a condition closely associated with atherosclerosis." (PMID 40953531, 2025). "This indicates that endothelial MerTK deficiency promotes SMC dysfunction in atherosclerosis." (PMID 40953531, 2025). "Thus, downregulation of MERTK by PA can also contribute to the defective efferocytosis and inflammation resolution associated with the pathogenesis of atherosclerosis." (PMID 40068774, 2025). "MerTK activity is implicated in a wide variety of functions involving the elimination of apoptotic cells and has recently been linked to cancers, auto-immune diseases, and atherosclerosis/stroke." (PMID 38928335, 2024).
atherosclerosis (continued). "MerTK deficiency leads to enhanced pathology in mouse models of atherosclerosis." (PMID 30980657, 2019). "Moreover, cultured splenocytes isolated from MerTK −/− KO mice showed enhanced production of pro-inflammatory cytokines and MerTK deficiency led to accelerated atherosclerosis." (PMID 31614787, 2019). "Consistent with this protective role for MerTK activity in atherosclerosis, loss of MerTK, either by genetic deletion or through models in which MerTK has been replaced by a version with an inactive kinase domain, results in increased lesion size and larger necrotic cores." (PMID 29379788, 2017). "Although MerTK mutation in macrophages or MerTK gene global knockout mice have been shown to exacerbate atherosclerotic plaque formation, the specific role of endothelial MerTK in atherosclerosis and its underlying mechanisms remain unclear." (PMID 40953531, 2025). "In addition, our study may also have clinical relevance for other endothelial MerTK-associated cardiovascular diseases, such as atherosclerosis and vascular aging." (PMID 39744231, 2025). "As the main receptor for efferocytosis, lower MerTK expression would be expected to cause impaired efferocytosis, accumulation of apoptotic and necrotic cells, and inflammation, which are processes associated with atherosclerosis, myocardial infarction, and aneurysm rupture." (PMID 38341954, 2024). "This study investigates the specific contribution of endothelial MerTK to atherosclerosis development." (PMID 40953531, 2025). "Our results align with prior studies on ADAM17, which also cleaves MerTK in lung injury and atherosclerosis models, highlighting conserved proteolytic mechanisms within the ADAM family." (PMID 41169382, 2025). "Macrophages synthesize putrescine from AC-derived arginine and ornithine to sustain efferocytosis, MerTK expression, IL-10 production, inflammation resolution, and, ultimately, atherosclerosis regression." (PMID 40833492, 2025). "Recent studies have shown that MerTK reduction in macrophages contributes to the aggravated atherosclerosis in diabetes-induced atherosclerosis." (PMID 41083981, 2025). "Big data analytics, human microarray analyses, proteomics, and a unique mouse model with MerTK deficiency in endothelial cells (MerTKflox/floxTie2Cre) were utilized to elucidate the role of endothelial MerTK in atherosclerosis development." (PMID 40953531, 2025). "Our findings provide strong evidence that endothelial MerTK impairment serves as a novel mechanism in promoting atherosclerosis development." (PMID 40953531, 2025). "This promotes us to investigate a novel mechanism of miR-218–5p/ECMerTK/MAPK axis in endothelial MerTK-mediated atherosclerosis." (PMID 40953531, 2025). "Here, we specifically assessed mitochondrial function to determine its contribution to endothelial MerTK-mediated atherosclerosis." (PMID 40953531, 2025). "Others have delivered payloads to enhance efferocytosis, such as nanoparticles presenting MerTK on their surface, which promote apoptotic cell clearance and significantly attenuate atherosclerosis in mice ​." (PMID 40172727, 2025). "Our data provides compelling evidence that endothelial MerTK impairment significantly accelerates atherosclerosis development, suggesting therapeutic restoration of endothelial MerTK function as a promising strategy to prevent atherosclerosis." (PMID 40953531, 2025). "Collectively, these findings reinforce the critical roles of MAPK signaling and TGFβ signaling in endothelial MerTK-mediated atherosclerosis." (PMID 40953531, 2025). "While prior studies have shown that ADAM17 can also cleave MerTK in ventilator-induced lung injury and atherosclerosis models, our findings underscore the distinct and context-specific function of ADAM8 in SICM pathogenesis." (PMID 41169382, 2025). "Our future study will also investigate the therapeutic potential of restoring endothelial MerTK expression in the prevention and treatment of atherosclerosis." (PMID 40953531, 2025).
atherosclerosis (continued). "This promotes us to focus on endothelial MerTK and investigate its role in atherosclerosis development." (PMID 40953531, 2025). "MERTK has been well investigated and shown to promote efferocytosis and increase fibrous cap formation in advanced atherosclerosis." (PMID 39531316, 2024). "Delivery of MerTK via magnetic navigated HMNVs restored MerTK in diabetic macrophages and thus rescued the efferocytosis capacity, serving as a promising therapeutic approach to alleviate atherosclerosis." (PMID 38614985, 2024). "Following ischemia/reperfusion-induced cardiac injury, MerTK undergoes cleavage similarly to the pattern observed in atherosclerosis in both humans and mice." (PMID 39660125, 2024). "In vivo, MerTK-/- aggravates abnormal endothelial thickening and endothelia dysfunction, impairing endothelial efferocytosis and promoting atherosclerosis." (PMID 38646649, 2024). "Similar to its role in atherosclerosis, MerTK activation also facilitates efferocytosis in myocardial infarction." (PMID 39660125, 2024). "Our findings provide another persuasive evidence for the role of MerTK in regulation of endothelial dysfunction and atherosclerosis." (PMID 38646649, 2024). "This indicates that inflammatory response plays an important role in MerTK inhibition and subsequent impaired efferocytosis in atherosclerosis." (PMID 38646649, 2024). "ADAM17 (a disintegrin and metalloprotease 17) is responsible for cleavage of MerTK, resulting in defective efferocytosis that contributes to accumulation of apoptotic cells and tissue injury in cardiovascular diseases including atherosclerosis." (PMID 38341954, 2024). "In conclusion, we provide evidence for a relationship between d-flow, MerTK and endothelial efferocytosis and its implications in atherosclerosis." (PMID 38646649, 2024). "Exogenous ligands, including recombinant Gas6, can target Axl/MerTK-mediated erythrophagocytosis akin to approaches used in atherosclerosis." (PMID 39660125, 2024). "In this study, we found that diabetic ApoE–/– mice showed aggravated atherosclerosis as hyperglycemia damaged the efferocytosis capacity at least partially due to decreased expression of Mer tyrosine kinase (MerTK) on macrophages." (PMID 38614985, 2024). "Future study needs to be performed with MerTK specifically knockout in ECs to clarify the role of endothelial MerTK in atherosclerosis." (PMID 38646649, 2024). "In plaque, compared with atherosclerosis alone group, MerTK significantly highly expressed in atherosclerosis accompanied with carotid stenosis and hypertension." (PMID 38341954, 2024). "We thus assessed the expression of the phagocytic receptors MERTK and TREM2, which have both been implicated in efferocytosis and necrotic core formation in atherosclerosis." (PMID 39531316, 2024). "As atherosclerosis progresses, persistent inflammatory stimuli lead to the cleavage of MerTK from the cell surface." (PMID 39660125, 2024). "Hybrid membrane nanovesicle-based MerTK protein delivery presents as a promising therapeutic approach for atherosclerosis management in patients with diabetes." (PMID 38614985, 2024). "Our further study here reveals that diabetes exacerbates atherosclerosis at least partially by damaging macrophage efferocytosis capacity via decreased MerTK." (PMID 38614985, 2024). "It has been shown that disruption of MERTK activity severely compromised injury resolution in atherosclerosis." (PMID 37615937, 2023). "In macrophages, MERTK was reported to influence atherosclerosis progression through apoptotic cell clearance." (PMID 36012766, 2022). "Defective MERTK expression leads to chronic inflammation and autoimmune diseases such as atherosclerosis, MS, systemic lupus erythematosus, rheumatoid arthritis and Crohn’s disease." (PMID 33912166, 2021). "We recently demonstrated that the LMP7 subunit promotes diet-induced atherosclerosis via inhibition of MERTK-mediated efferocytosis." (PMID 33195259, 2020).